VCAN (versican)
Diseases named in the same sentence as VCAN in open-access papers (continued):
Sharing a sentence is not in itself a finding about the gene and the disease.
cancer (continued). "Here we focus on versican, because it has been shown to have direct association with immune cell phenotype and trafficking in inflammatory diseases and development, and we consider here how these roles for versican may translate to cancer immunity." (PMID 34527586, 2021). "Previous data showed that the radiosensitivity of cancers could be regulated by circRNAs, such as circ_0086720, circRNA versican, and circRNA Cyclin B2." (PMID 33882945, 2021). "Although VCAN has been studied in several cancers, its research in GC is still unclear." (PMID 33631054, 2021). "We suspect that VCAN may play a role in the cell-ECM adhesion interactions during cancer progression and may be used as a prognostic marker and therapeutic target for the treatment of the disease." (PMID 33604385, 2021). "Furthermore, we also explored the potential mechanism of VCAN being involved in cancer progression, and we realized that hypomethylation of VCAN was associated with stage, histological subtypes, and metastasis of BLCA." (PMID 33604385, 2021). "Versican is a large CSPG involved in regulating cell proliferation in several cancer types." (PMID 32825245, 2020). "Interestingly, in tumors, human cancer stem cells synthesize and secrete prominent pericellular coat matrices enriched in hyaluronan and versican." (PMID 32265939, 2020). "Finally, co-localization of ADAMTS-15, VCAN and versikine suggests ADAMTS-15 regulates VCAN cleavage as a likely mechanism to impact on cancer progression." (PMID 32354091, 2020). "On the other hand, lack of versican expression in a mouse fibrosarcoma model resulted in a decrease in the number and density of cancer-associated fibroblasts (CAFs) in stroma." (PMID 32265939, 2020). "Notably, expression of distinct versican isotypes was shown to facilitate cancer progression in multiple cancer types." (PMID 32984308, 2020). "Indeed, one of the critical effects of VCAN aberration is generating a microenvironment conducive for cancer cell migration and invasion." (PMID 31777586, 2019). "Since versican has been previously demonstrated to be up-regulated by TGF-β in cancer scenarios, we investigated if macrophages could be the source of secreted TGF-β1." (PMID 31334111, 2019). "Transcripts of Versican, Vegf-c, Bcl-2, Mmp-9, Il-6 and KC were up-modulated in pituitaries isolated from transgenic mice; in in vitro studies, exogenous hCG has been shown to up-modulate transcription and expression of these molecules in cancer cells." (PMID 30410667, 2018). "In some tumors, increased levels of versican have been found, which suggests that it might contribute to cancer progression." (PMID 29212223, 2017). "Elucidating the role of the IL-17A/miR-23b/versican pathway might enlarge our understanding of the interaction between inflammatory microenvironment and cancer progression, which can be exploited for potential immunotherapeutic and diagnostic target in TSCC." (PMID 28035060, 2017). "We initially determined versican expression by several cancer cell lines." (PMID 29222454, 2017). "A Sharpin/Versican axis could be an attractive therapeutic target for this currently untreatable cancer." (PMID 27941932, 2016). "Although CXCL8 and VCAN tend to increase in macrophages cultured with both cancer cells, statistical significance was only achieved for the anti-inflammatory marker VCAN in co-cultures with SW1463 and for the pro-inflammatory marker CXCL8 marker in co-cultures with RKO cells." (PMID 27513864, 2016). "Our previous studies have shown that the oil fraction of Ganoderma spores could induce death in versican-transformed cancer cells." (PMID 27713910, 2016). "Thus, our data suggest a new approach for the modulation of Versican isoform synthesis for the development of therapeutics against cancer." (PMID 26515726, 2015). "Cancer cell-derived secretomes induced versican and biglycan expression in fibroblasts." (PMID 25593993, 2014).
cancer (continued). "There is increasing evidence that ADAMTS proteases play an important role in the cleavage of versican, and the local accumulation of versican fragments generated by ADAMTS digestion may also promote cancer cell motility and invasion." (PMID 21541039, 2011). "Manipulation of the versican catabolic pathways may provide novel therapeutic targets against cancer invasion and metastasis." (PMID 21541039, 2011). "miR-138, whose expression is correlated with many different types of cancers and diseases, is also involved in cardiac patterning, specifically through the regulation of expression of genes such as aldehyde dehydrogenase (Aldh) -1a2 and versican." (PMID 21931743, 2011). "Ongoing study on the mechanisms of cancer invasiveness and cellular signaling will further advance our knowledge on how extracellular matrix and cellular factors such as versican and EGFR signaling impact patient outcomes and can be modulated in response to treatment." (PMID 22096483, 2011). "No studies to date have yet investigated whether these inhibitors are effective in inhibiting the effects of versican in cancer models." (PMID 21541039, 2011). "Versican may facilitate the local expansion of cancer cells and, subsequently, the invasion and formation of distant metastases by decreasing cell-matrix adhesion, sufficient to promote cancer cell migration through the extracellular matrix." (PMID 21791066, 2011). "However, there are no data to show that such approaches are effective in inhibiting the effects of versican in cancer cell models." (PMID 22096483, 2011). "In contrast, versican was significantly increased only in carcinomas with MAMCs (median ± SE: 42.0 ± 9.1) and MD (22.5 ± 10.1) as compared to normal breast tissue with MAMCs (14.0 ± 5.8), MD (11.0 ± 4.4) and normal breast tissue without mammographic findings (10.0 ± 2.0)." (PMID 21791066, 2011). "The cancer-promoting functions of versican may act through regulating growth factor activity and by interacting with immune and stromal cells, functions which could be modified by alterations to sulfation." (PMID 20885998, 2010). "Finally, both CRP and FFV PEVs significantly upregulated gene expression of ECM components (e.g. MMP14, MMP16, collagen type V alpha 1 chain, versican) as well as the genes SERPINE1 and PMEPA1, which are associated with epithelial-to-mesenchymal transition in various cancer types." (PMID 39695652, 2024). "Notwithstanding cancers with other mutations and other myeloid cells like neutrophils and mast cells that might also fuel tumors with IL-1β, we define here a non-oncogene addiction of KRAS and IL-1β, in tandem with their partners in crime VCAN and IKKβ." (PMID 36980752, 2023). "However, there have been limited reports on the role of VCAN in cancer lymphatic metastasis." (PMID 37108649, 2023). "Moreover, specific EVP adhesion proteins (e.g., CD36, TN-C, THBS2, and VCAN) may also be pan-cancer markers." (PMID 37350937, 2023). "Our results revealed that VCAN promoted ECM structural composition and molecular mechanisms such as collagen expression in UTUC and was associated with invasion and metastatic signaling molecules, indicating that the mechanisms of action of the same gene can also vary across cancer types." (PMID 37108649, 2023). "Moreover, the role of VCAN in EMT during cancer seems to be isoform specific." (PMID 36358747, 2022). "Therefore, the combination of inhibitors against these immunological checkpoints and VCAN inhibitors may potentially enhance the anti-cancer effect in patients with HCC." (PMID 35812745, 2022). "Therefore, the observed downregulation of BCAN, NCAN, and VCAN in Etoposide resistant RB cells contrasts with the expression pattern in adult cancer but might represent the expression pattern in childhood tumors." (PMID 32560557, 2020). "Thus, various cancer cell lines differ widely in their versican expression levels." (PMID 29222454, 2017).
cancer (continued). "Moreover, elevated versican is reported to increase cancer cell motility and invasion." (PMID 28035060, 2017). "However, different versican isoforms trigger different responses in cancer cells." (PMID 27490467, 2016). "To gain further insight into whether it is likely for the overexpressed versican to be degraded by ADAMTS as a cancer invasive mechanism, we examined ADAMTS-1, -4 and -5 expression in healthy and cancerous colon tissues and also in colon cancer cell lines of different metastatic potential." (PMID 25786261, 2015). "Therefore, manipulation of versican expression with relevant EGFR signaling alteration may provide novel therapeutic mechanism against EMT process in cancer." (PMID 26515726, 2015). "Since versican and fibulin peptides are potentially difficult to detect in complex mixtures using mass spectrometry (because they are large, heavily glycosylated proteins), and because of their implication in cancer, we decided to further validate these two ECM proteins using IHC." (PMID 21975223, 2011). "Versican (VCAN)-AS1 is an endogenous RNA that targets signal transducer and activator of STAT3 to inhibit miR-106a-5p and promotes the growth of cancer cells by blocking the STAT3/HIF-1α axis." (PMID 41614928, 2026). "In particular, FN1, VCAN, and LRRC15 are markers of BMSCs which also co-modularized with COL10A1 in cancer; all three genes are involved in cell migration, and FN1 contributes directly to osteoblast mineralization as well as metastasis." (PMID 39939916, 2025). "As CD26 expression can influence EMT induction in cancer, we analyzed the correlation of CD26 with the EMT phase markers E-cadherin, Vimentin, β-catenin, Elastin, Periostin, and Versican." (PMID 41426321, 2025). "Despite the low prevalence of VCAN-undetectable tumors within the ER+ cohort, there was a trend toward more CD8+ T cells within the epithelial compartment of VCAN-undetectable cancers compared to VCAN-detectable tumors (p = 0.065)." (PMID 40361362, 2025). "Maximum of the cancers displayed the pattern, with enhanced expression of IL19, TGFβ-1, CXCR4, BMP1, VCAN, and WNT2 protein levels in the samples of KICH, KIRC, LUAD, LUSC especially BRCA when compared to normal samples." (PMID 41348904, 2025). "VCAN's fragments after regulated proteolysis by ADAMTS and MMPs, known as VCAN‐matrikines, have supporting roles in these diverse cancer‐promoting processes." (PMID 40542654, 2025). "Specifically, genes such as STC1 (PAI 6: Vertebrata), VCAN (PAI 7: Euteleostomi), and SPP1 (PAI 9: Eutheria)—key regulators of such hallmarks of cancer as angiogenesis and metastasis in tumors." (PMID 40507851, 2025). "However, disturbances in the hyaluronan-versican interaction may affect cancer development." (PMID 40656954, 2025). "VCAN immunocytochemistry was performed on human PDA samples (n = 3) and normal pancreas (n = 3) next to cancer tissues." (PMID 39098880, 2024). "The upregulation of VCAN mediated by INHBA can promote the migration and proliferation of cancer cells in CRC." (PMID 38730335, 2024). "For example, versican, one of the ADAMTS1 substrates, was reported to promote invasive phenotypes of gastric and ovarian cancer cells." (PMID 38263290, 2024). "Here we have evaluated the expression of IGF1, CCL5, IL-8, VCAN and RTN4 in peritumoral AT of women with BC, to investigate their potential role as markers of cancer progression." (PMID 39501160, 2024).
cancer (continued). "VCAN and ACAN are recognized as substrates of ADAMTS1, influencing cancer progression or metastasis." (PMID 39333870, 2024). "When VCAN forms complexes with molecules such as HA and CD44, the viscosity and elasticity of the ECM increase, shaping an environment conducive to cancer cell proliferation and migration." (PMID 38791985, 2024). "We have found that VCAN and IGF1 in peritumoral AT correlated with cancer Ki67 and OCT4, respectively, thereby providing an index of cancer proliferation and aggressiveness." (PMID 39501160, 2024). "VCAN also induced IKKβ in primary murine BMDM, which were verified by microarray to overexpress > 10-fold over cancer cells TLR1, TLR2, TLR6-9, and TLR13." (PMID 36980752, 2023). "Examples of PGs that have been well studied in the cancer context include HS PG, perlecan (HSPG2), and the CS PG, versican (VCAN)." (PMID 36923282, 2022). "Versican, a major CSPG, plays an important role in cancer progression via regulating cell adhesion, migration, proliferation, differentiation, and angiogenesis through both its core protein and the structure of the attached CS chains." (PMID 36230789, 2022). "Versican is an important PSGL-1 ligand that should be investigated further and considered as a target for cancer immunotherapy." (PMID 33708224, 2021). "EV biomarkers of note include the stromal proteins versican (VCAN) and thrombospondin 2 (TSP2), which were part of a highly accurate (~90% sensitivity/95% specificity) 16 EV pan-cancer signature." (PMID 34298706, 2021). "Several studies have showed that SERPINA1, APOA1, VCAN, and APOB mediated the development of cancer chemotherapy resistance." (PMID 34737677, 2021). "Versican is a relevant PSGL-1 ligand to consider during therapeutic design, as versican has been found to be increased in a number of cancers." (PMID 33708224, 2021). "Versican (VCAN) is a chondroitin sulfate proteoglycan which is important for tumorigenesis and the development of cancer." (PMID 33604385, 2021). "Affected genes included FGFR1, IRS1, CLDN4, GRB7, and VCAN, while EZR and MYC were commonly affected in at least four out of five progression stages of the selected cancer levels." (PMID 34069906, 2021). "Across the 18 cancers in their study, certain proteins stood out as pan-cancer markers such as THBS2, VCAN, SRRT, and TNC." (PMID 39698114, 2020). "In our study, we analyzed the Cancer Cell Line Encyclopedia (CCLE), The Cancer Genome Atlas (TCGA), and the Genomics of Drug Sensitivity in Cancer (GDSC) database, to select six genes (FBN1, FN1, HGF, MMP9, THBS1, and VCAN) as target genes." (PMID 33014013, 2020). "Emerging as a key player in the progression of numerous cancers is ECM regulation, particularly through the PG VCAN." (PMID 32354091, 2020). "Relative PAM, STC1, and HDAC4 expression were down-regulated, whereas CASP6, CHST6, SLC16A3, TPI1, KDELR3, VCAN, and CLDN9 were highly expressed in carcinoma tissues compared to the para-carcinoma tissues." (PMID 33424916, 2020). "As described for cancer development, ADAMTS-1 is an important factor in regulating versican activity through versican proteolysis events." (PMID 31508361, 2019). "This is further supported by other genes that correlated closely in many cancer forms such as FAP, PDGFRB, THBS2 and VCAN which are also markers for matrix-producing cells and in some cases also for cancer-associated fibroblasts." (PMID 27809802, 2016). "ADAM12, VCAN and MET protein expression levels were also detected through western blot in cancer cells transfected with miR-144 mimics." (PMID 25927670, 2015). "Over-expression of these proteases is consistent with the requirements of carcinoma cells to remove proteoglycans of ECM, such as versican and aggrecan, as a complementary mechanism to collagen degradation by collagenases and gelatinases." (PMID 25786261, 2015). "Genes that are implicated in angiogenesis were also identified; both VCAN and ANTXR1 promote angiogenesis for cancer progression." (PMID 23372686, 2013).
cancer (continued). "When PanIN samples were compared to PDACs, the most commonly up-regulated genes in the cancers were POSTN, COL1A2, SULF1, FN1, IGHM, VCAN and XIST, and these down-regulated were PGC and PPY." (PMID 23372777, 2013). "Cancers without detectable stromal VCAN staining had the greatest number of CD8+ T cells/HPF compared to those with detectable VCAN staining (p = 0.012)." (PMID 40361362, 2025). "Interestingly, after the addition of the anti-cancer drug DOX, VCAN knockdown can have a synergistic effect with DOX, which can further significantly inhibit the proliferation of A431 cells." (PMID 40386063, 2025). "Besides CD44, VCAN binds to TLRs, promoting the secretion of pro‐inflammatory cytokines (TNF‐α, IL‐6) that prevent cancer cell apoptosis and enhance metastasis." (PMID 40542654, 2025). "While we found greater CD8+ T cells across TNBC cancers compared to the ER+/PR+ cancers at large, a lack of VCAN identified patients with a similar presence of CD8+ T cells regardless of ER/PR status." (PMID 40361362, 2025). "Additionally, we found that TUBA1B+ TAMs, C1QC+ TAMs and IL1B+ TAMs were predominant in early-stage tumors, whereas VCAN+ TAMs, SLC40A1+ TAMs and APOC1+ TAMs had higher proportions in patients with advanced cancer." (PMID 39232806, 2024). "Human pan-cancer and experimental NF-κB reporter, transcriptome, and proteome screens reveal that KRAS-mutant tumors trigger macrophage IKKβ activation and IL-1β release via secretory versican." (PMID 36980752, 2023). "Importantly, we show that targeting IL-1β and/or versican can be an effective treatment for KRAS-mutant cancers, holding great promise for cancer patients." (PMID 36980752, 2023). "We also observed differential expression of cancer-metastasis-inducing genes, such as ZEB1, MMP9, CLDN3, TWIST1 and N-cadherin, between LVI(+) and LVI(−) samples in some patients, indicating a correlation of VCAN with EMT genes in LVI(+) samples." (PMID 37108649, 2023). "Because of these variables, VCAN can promote pleiotropic downstream effects; therefore, determining the specific functions of VCAN in cancer is not trivial." (PMID 36923282, 2022). "VCAN is a member of the large chondroitin sulfate proteoglycan family with hyaluronate-binding capacities located in the ECM and inhibits apoptosis and exerts functions in metastasis through the ECM remodeling pathway in multiple types of cancers." (PMID 35625898, 2022). "CAF produce numerous factors acting on cancer cells to promote glycolytic metabolism, proliferation, invasion, angiogenesis and metastatic colonisation, including CCL5, CXCL10, IL‐6, TGFα, SDF and versican." (PMID 34841720, 2021). "Versican, an ECM glycoprotein that mediates tissue inflammation, is also over-expressed in cancer." (PMID 33187209, 2020). "Versican mRNA and protein levels have not been systematically compared in experimentally used cancer cell lines and tumors arising from them." (PMID 29222454, 2017). "Increased versican, which may be related to modulated ADAMTS expression, is also observed in canine colonic adenomas and carcinomas." (PMID 25786261, 2015). "A study identified VCAN as a key upregulated gene in CAFs that promotes the motility and invasion of OC cells by activating the nuclear factor-κB signaling pathway and upregulating CD44, MMP-9, and hyaluronan-mediated motility receptor expression in cancer cells." (PMID 40369674, 2025). "This study does not provide evidence of whether the increased VCAN gene expression in PSC has a protective or cancer-permissive effect; hence, obtaining a better understanding of the pro- and anti-tumorigenic functions of VCAN is essential." (PMID 39098880, 2024). "Moreover, we have analysed peritumoral AT VCAN and RTN4 following a large in silico study mainly based on transcriptomic and proteomic data that have reported their presence in mammary AT secretome and their contribution to cancer phenotypes." (PMID 39501160, 2024).